SELE (selectin E)
Diseases named in the same sentence as SELE in open-access papers (continued):
Sharing a sentence is not in itself a finding about the gene and the disease.
lupus nephritis (3 papers, 2011 to 2014). Glomerulonephritis in the context of systemic lupus erythematosus. "We therefore speculate that sE-selectin levels may not be directly related to renal E-selectin expression levels and also may not be significantly associated with the activity of lupus nephritis." (PMID 25400916, 2013).
Sjögren’s syndrome (3 papers, 2022 to 2023). "SELE expression is also found positively correlated with the duration of Sjogren’s syndrome, characterised by dysregulation of circulating immune cells, T cells and antigen presenting cells and vascular endothelial extravasation." (PMID 37849501, 2023).
African trypanosomiasis (2 papers, 2021 to 2025). "KEGG pathway enrichment analysis of these shared genes (corrected p < 0.05) revealed significant overrepresentation in glutamatergic synapse (encompassing HOMER1, HOMER2, PLCB4, and ADCY9) and African trypanosomiasis (containing SELE, MYD88, and PLCB4)." (PMID 41153960, 2025).
cutaneous squamous cell carcinoma (2 papers, 2016 to 2023). "In cutaneous squamous cell carcinoma, MDSCs impair vascular E-selectin expression through iNOS-induced NO production, and N(ω)-nitro-L-arginine(L-NNA), an iNOS inhibitor, restored vascular E-selectin expression to enhance T cell recruitment." (PMID 37277776, 2023).
steatosis (2 papers, 2017 to 2020). Increased lipid within the cytoplasm of cells. "CBD ameliorates alcohol-induced liver injury by attenuating inflammatory response involving E-selectin expression and neutrophil recruitment, and consequent oxidative/nitrative stress, in addition to attenuation of the alcohol-induced hepatic metabolic dysregulation and steatosis." (PMID 28935932, 2017).
thalassaemia (2 papers, 2018 to 2025). "As thalassaemia MPs could induce TF, IL-6, IL-8, ICAM-1, VCAM-1 and E-selectin expression, the potential functional consequences of MPs influence on the adhesion of endothelial cells and monocytes was examined." (PMID 30158562, 2018).
ZIKV infection (2 papers, 2019 to 2020). "We observed that ZIKV infection led to selective upregulation of CAMs (VCAM1, ICAM1, and SELE) whereas PECAM was downregulated upon ZIKV AF infection (≤2-fold, P value ≤ 0.05 compared to CT), confirming the data obtained previously with the array." (PMID 32753493, 2020).
aneurysm (1 paper, 2022). Bulging or ballooning in an area of an artery secondary to arterial wall weakening. "Genes with inflammatory and immune functions, including interleukin 8 (IL-8), prostaglandin-endoperoxidase synthase 2 (COX2), selectin E (SELE), and prokineticin 2 (PROK2), were confirmed to be overexpressed in aneurysm rupture lesions." (PMID 36482903, 2022).
chronic rhinosinusitis (1 paper, 2014). Chronic form of sinusitis. "Protein analysis by Western blotting showed strongly decreased E-selectin expression levels in nasal polyps compared to the inferior turbinates of chronic rhinosinusitis patients adapted to β-actin." (PMID 24995349, 2014).
dermatitis (1 paper, 2025). An inflammatory process affecting the skin. "Transcriptomic analysis and machine-learning models enable patient stratification, allowing for the identification of biomarkers such as ADAM8, CD47, BATF, SELE, IL-37 that may aid in diagnosis and differentiating ACD from other forms of dermatitis." (PMID 40181807, 2025).
gastric adenocarcinoma (1 paper, 2023). "According to the boxplot analysis, the mRNA levels of DOCK4, GNAS, TGFB1, SELE, and SMARCE1 demonstrated a considerably higher expression in gastric adenocarcinoma than in healthy controls." (PMID 37037466, 2023).
gastroschisis (1 paper, 2024). Gastroschisis is marked by viscera protruding, without a covering sac, from the fetal abdomen on the right lateral base of the umbilicus. "Besides ICAM1, the study from the Torfs group also identified a heterozygous/homozygous variant of NOS3, NPPA, ADD1, SERPINE1, and SELE, genes involved with cell–cell interactions, inflammation, or blood pressure, associated with gastroschisis." (PMID 39728087, 2024).
geographic atrophy (1 paper, 2011). "Patients were divided into AMD subgroups (dry AMD, wet AMD, and geographic atrophy and further analyzed for associations with the SNPs in SELE, SELL, and SELP." (PMID 21521525, 2011).
histiocytic sarcoma (1 paper, 2025). An aggressive malignant neoplasm with a poor response to therapy, usually presenting as stage III/IV disease. "Furthermore, the upregulation of SELE may synergistically enhance the metastatic potential of canine histiocytic sarcoma, highlighting their roles in tumor progression." (PMID 40724877, 2025).
Lewy body dementia (1 paper, 2023). A progressive form of dementia characterized by the presence of protein deposits called Lewy bodies in the midbrain and cerebral cortex, and loss of cholinergic and dopaminergic neurons. "The SELE Ser128Arg gene polymorphism has also been associated with AD and SELE polymorphisms are also associated with Lewy body dementias." (PMID 37849501, 2023).
mastitis (1 paper, 2024). Inflammation of breast tissue during lactation or postpartum due to an obstructed duct or infection. "Notably, the three target genes, COL1, MMP2, and SELE, in AGE-RAGE signaling can all be affected by quercetin, which suggests that quercetin may be the most promising GYS compound for mastitis therapy." (PMID 38630770, 2024).
meningococcal infection (1 paper, 2025). Infections with bacteria of the species neisseria meningitidis. "To assess whether this aspect of the infection can be recapitulated within the VoC upon meningococcal infection, we examined E-selectin expression in response to inflammatory stimuli and infection." (PMID 41406015, 2025).
myeloid leukemia (1 paper, 2024). A clonal proliferation of myeloid cells and their precursors in the bone marrow, peripheral blood, and spleen. "While reduced infiltration of adoptively infused lymphocytes has not been addressed in myeloid leukemia, it is well known that AML development triggers increased E-selectin expression on surrounding endothelial cells in the BM niche causing chemorefractoriness and AML dormancy." (PMID 38182818, 2024).
nasal polyps (1 paper, 2014). "Median expression of E-selectin was decreased (0.22-fold, n = 14), while P-selectin expression was increased (2.37-fold, n = 15) in nasal polyps compared to associated inferior turbinates." (PMID 24995349, 2014). "Analysis showed a strongly decreased E-selectin expression in nasal polyps with a significant difference between eosinophil and neutrophil counts in nasal polyps and balanced counts in inferior turbinates." (PMID 24995349, 2014).
tumor (313 papers, 2000 to 2026). "In contrast, Venous‐1 cell subsets express the specific endothelial cell genes IL‐33, MADCAM1, SELP, and SELE, which are closely associated with leukocyte adhesion, angiogenesis, and tumor progression." (PMID 40860436, 2025). "TFs of AP-1, regulating TNFα, IL-6 and SELE are implicated as oncogenes or tumor suppressors in many cancers with drug development programs targeting cJun, JunB, JunD, cFos, FosB, Fra1 and Fra2." (PMID 36371231, 2022). "E-selectin overexpression is associated with tumor metastasis, and studies have found that E-selectin expressed in a variety of tumor tissues, such as NPC." (PMID 34103070, 2021). "Accordingly, E-selectin expression in tumor-associated vessels is elevated in different types of carcinomas, and the abundance of sLex positive immune infiltrates in the tumor is inversely associated with prognosis." (PMID 32204492, 2020). "Overall, ESTA-1 binding to the tumor associated vessels was highly correlated with E-selectin expression as indicated by ESTA/E-sel ratios for breast (ratio = 0.89), ovarian (ratio = 1) and skin (ratio = 1) carcinomas." (PMID 20927342, 2010). "Interestingly, when SCC samples were treated with a TLR-7 agonist, imiquimod, tumor vessels up-regulated E-selectin expression causing an increase in CLA+ CD8+ T cell influx into the tumor, a decrease in Treg frequency and tumor regression." (PMID 31231358, 2019). "ESTA-1 also bound specifically to the inflamed tumor-associated vasculature of human carcinomas derived from breast, ovarian, and skin but not to normal organs, and this binding was highly associated with the E-selectin expression level." (PMID 20927342, 2010). "The main purpose of the nanoparticle was to specifically target tumor vascular endothelial cells, thanks to the peptide’s ability to mimic selectin E. Release of podophyllotoxin would occur after the GSH-responsive break of the conjugate disulfide bond." (PMID 40005983, 2025). "CCL12, another chemokine expressed in the PMN, attracts Mo-MDSCs to the site before metastasis, prompting them to secrete IL-1β, which stimulates E-selectin expression and facilitates tumor cell attachment to the endothelium." (PMID 40427136, 2025). "In liver colorectal metastasis, metastatic cancer cells trigger the adhesion molecule E-selectin expression in liver endothelial cells, facilitating tumor cell arrest and metastasis." (PMID 39962271, 2025). "Conversely, E-Selectin expression in endothelial cells at the primary tumor site promotes better local control because of better immune cell infiltration." (PMID 40071851, 2025). "By releasing IL-1β, monocytes promote E-selectin expression on endothelial cells, enhancing the adhesion of tumor cells to the vascular endothelium." (PMID 40427136, 2025). "Regarding the input pathways in target cells, the receptors associated with C2 ALOX5+MCs were primarily CD99, SELE, and SPP1, while the receptors related to tumor cells included TWEAK, CEACAM, and CD96." (PMID 39224598, 2024). "The production of inflammatory cytokines leads to the promotion of adhesion of circulating tumor cells to the vascular endothelium of distant organs by enhancing the E-selectin expression." (PMID 35965580, 2022). "Lange and colleagues show that the multiple-myeloma drug bortezomib counteracts the solid primary-tumor-mediated induction of E-selectin expression in the lung, thereby blocking tumor cell extravasation and thus lung metastasis in vivo." (PMID 35031433, 2022). "SELE, a selectin, is a cell adhesion molecule that contributes significantly to tumorigenesis and tumor progression." (PMID 33907270, 2021). "To determine if expression of E-selectin played an important role in tumour cell adhesion and if LPS-induced tumour cell adhesion depended on E-selectin expression, we knocked down E-selectin in HUVEC and analyzed tumour cell adherence in both AGS and NUGC3." (PMID 33737522, 2021).
tumor (continued). "Cluster 5 (tumor core EC type III: Co3), were mainly derived from tumor core and were characterized by upregulation of immune-activated genes including IL1B, ACKR1, SELE, and VACM1, which are associated with inflammation and immune cell recruitment." (PMID 34228647, 2021). "Our findings indicated that MP suppressed E-selectin expression in the vascular endothelium, which inhibited tumour cell binding to endothelial cells." (PMID 33737522, 2021). "Again, this is promoted by the interaction of tumor cells with ECs, which leads to a higher E-selectin expression on tumor endothelium." (PMID 34073394, 2021). "Gene-gene interactions were detected in the relapse group; CCL5, GZMB, IL2RA, SELE, and CCL8 interacted with CCR5 in both the pCR and relapse groups and were associated with tumour progression, and metastasis." (PMID 33138797, 2020). "Tumor growth is also suppressed when E-selectin expression in LSECs is inhibited through the prevention of angiogenesis, suggesting E-selectin’s importance in metastasis progression in the liver." (PMID 33262947, 2020). "E-selectin expressed on activated endothelial cells binds to sialylated ligands on the surface of circulating tumor cells slowing them down, which is a key step prior to their extravasation from the circulatory system." (PMID 32872308, 2020). "IL-1β was produced by monocytic MDSCs in the premetastatic lungs, promoted E-selectin expression, and led to tumor cell adhesion to the vascular endothelium." (PMID 33322216, 2020). "Nonetheless, rolling of human bone-metastatic prostate tumor cells has been reported, and relies on E-selectin expression on bone marrow endothelial cells and the complimentary expression of cognate ligands on the tumor cells." (PMID 31497019, 2019). "Inhibition of VEGF increases E-selectin expression on the tumor vascular endothelium and promotes an increase in T cell tumor invasion." (PMID 30845711, 2019). "We showed that ANP inhibits the tumor cell adhesion to the vascular endothelium by suppressing E-selectin expression, which has a central role in the adhesion of tumor cells to endothelial cells." (PMID 29035170, 2017). "After 6 h of exposure to tumor-derived EV (pretreated with factor VIIa and FX) in vitro, endothelial cells upregulated E-selectin expression and secreted IL-8." (PMID 29164060, 2017). "With immunofluorescent microscopy, E-selectin expression was observed on a subpopulation of E4+ HUVEC exposed to tumor-derived EV and was abolished with FPRCK." (PMID 29164060, 2017). "In contrast, anti-E-selectin antibodies and antisense oligonucleotides that inhibit E-selectin expression impair experimental liver metastasis of murine and human tumor cells." (PMID 21722370, 2011). "Unlike angiogenic factors such as integrins and vascular endothelial growth factor receptor, E-selectin expression was detected in both the existing mature vessels and the microvessels in the tumor." (PMID 20927342, 2010). "First, immunohistochemical analysis was performed to evaluate the level of E-selectin expression on the tumor vasculature using paraffin sections derived from three types of carcinomas including breast, ovarian, and skin." (PMID 20927342, 2010). "Pharmacologic reduction of E-selectin expression by approximately 60 % (using the clinically approved proteasome inhibitor bortezomib) is in case of these tumor cell lines sufficient to impair endothelial adhesion in vitro and spontaneous lung metastasis in vivo." (PMID 39547084, 2025). "In addition, it has been reported that E-selectin enhances tumor cell adhesion, metastasis, and diffusion, and L-selectin can enhance tumor cell exosmosis by mediating leukocyte aggregation." (PMID 37765064, 2023). "Tumor cells directly or indirectly recruit inflammatory monocytes by releasing chemokines (cc-chemokine ligand 2 (CCL2)) or inducing local endothelial activation (E-selectin expression)." (PMID 37046617, 2023).
tumor (continued). "Increasing research also suggests that E-selectin (SELE) may increase tumor angiogenesis and the development of cancer." (PMID 36617649, 2022). "This low affinity might explain why the incomplete effect of BZM on E-selectin expression is sufficient to block adhesion and thus metastasis specifically in this subset of tumor models." (PMID 35031433, 2022). "Metastatic tumor cells are directed to such foci of increased E-selectin expression in the lung." (PMID 35031433, 2022). "Indeed, the inhibition of these enzymes in metastatic cancer cells was reported to inhibit E-selectin expression and their adhesion on endothelial cells leading to repression of metastases formation in the liver of tumor cells-inoculated mice." (PMID 35493456, 2022). "Moreover, we showed that MP inhibited LPS-induced tumour cell adhesion that was dependent on E-selectin expression." (PMID 33737522, 2021). "Furthermore, E-selectin expression on ECs is required for myeloid cell infiltration in different mouse tumor models." (PMID 34073394, 2021). "Early studies have shown that the presence of tumor cells in hepatic circulation can trigger a rapid induction of E-selectin expression in LSECs, which could serve as adhesive molecules that facilitate tumor cell colonization." (PMID 33262947, 2020). "Furthermore, CCL12 promotes M-MDSCs to migrate to premetastatic lungs in melanoma cell-bearing mice and increases IL-1β and E-selectin expression before the arrival of tumor cells, which is beneficial for tumor cell arrest of endothelial cells." (PMID 30792719, 2019). "E-selectin expression was present both in the bone marrow and tumor cells." (PMID 31877673, 2019). "Thus, at all inflammatory sites of humans (including tumor endothelial beds), vascular E-selectin expression is more pronounced than that of P-selectin, and E-selectin also has higher baseline expression than P-selectin in human marrow and skin." (PMID 30687313, 2018). "Recruitment of inflammatory classical monocytes and pDCs to tumor-cell-activated endothelium has also been reported to be dependent on E-selectin expression, which can lead to an inhibition of the tumor-specific immune defense response and induction of tolerance." (PMID 29403469, 2017). "In addition, MDSC-caused inhibition of E-selectin expression prevents tumor-specific T cell traffic into the tumor, thus, contributing a mechanism by which MDSC impair anti-tumor immunity." (PMID 27391954, 2016). "It is interesting to note that while significant and functionally relevant glycocalyx changes were observed within 30 min, the effects of longer treatment of cerebral endothelial cells with lung tumour secreted-factors induced even greater levels of E-selectin exposure and tumour cell adhesion." (PMID 26407999, 2015). "However, E-selectin expression at the surface of endothelial cells is induced by tumor-derived IL-1α and monocyte-induced IL-1β in inflammatory metastatic sites." (PMID 25255877, 2014). "Based on these transcriptomic results, suppression of CCN2, FGFR2, and SELE may inhibit tumor proliferation, metastasis, or angiogenesis, while upregulation of CDH1 and CXCL10 could enhance cellular adhesion and antitumor immune responses, offering promising avenues for therapeutic intervention." (PMID 40724877, 2025). "Moreover, shear flow assays, mimicking the potential interaction between tumor cells and endothelium, showed that orospheres are remarkably more able to adhere to E-selectin-expressing cell layer, a feature that is of paramount importance for distant metastasis formation." (PMID 25428916, 2015). "However, it is unknown if CTCs from PCa patients interact with E-selectin expressed on endothelium, initiating a route for tumor metastases." (PMID 24386459, 2013). "The E-selectin gene (SELE) is part of the selectin family of cell adhesion molecules, which is crucial for the adhesion of circulating tumor cells to the vascular endothelium, facilitating metastasis." (PMID 40724877, 2025).